CIB2 (calcium and integrin binding family member 2)
Diseases named in the same sentence as CIB2 in open-access papers (continued):
Sharing a sentence is not in itself a finding about the gene and the disease.
lung carcinoma (2 papers, 2020 to 2024). "A4GALT, PSMA1, and CIB2 are all among the potential oncogenes identified, since high expression of their mRNAs is significantly associated with lower lung cancer patient survival." (PMID 33227088, 2020). "To clarify the major molecular mechanism by which CIB2 increases gefitinib resistance, we demonstrated that raised CIB2 in lung cancer cells promoted epithelial-to-mesenchymal transition (EMT) through upregulation of ZEB1." (PMID 39264588, 2024). "In our research, high expression levels of CIB2 were found in gefitinib-resistant lung cancer cells." (PMID 39264588, 2024). "ZEB1 expression levels have been shown to be correlated with EMT pathway activation in lung cancer tissues, suggesting the crucial role of CIB2/ZEB1 in tumor metastasis." (PMID 39264588, 2024). "Our investigation of CIB2 in cancer development and chemoresistance will provide a broad vision in lung cancer." (PMID 39264588, 2024). "To investigate the function of CIB2 in lung cancer cells, we first detected that CIB2 knockout PC-9G cells grew more slowly and CIB2 overexpression in the PC-9 cells promoted cell proliferation." (PMID 39264588, 2024). "In contrast to A4GALT, CIB2, and PSMA1, high expression of IRF4 is associated with higher lung cancer patient survival." (PMID 33227088, 2020). "Inhibition of CIB2 in gefitinib-resistant lung cancer cells significantly induced cell apoptosis." (PMID 39264588, 2024). "Interestingly, FOSL1 levels were found to have a positive relationship with CIB2 levels by correlation coefficient analysis using the GEPIA database in lung cancer patient samples." (PMID 39264588, 2024). "Thus, our findings conveyed that CIB2 functioned as an oncogene in lung cancer and promoted tumor development." (PMID 39264588, 2024). "In conclusion, our study first demonstrated that FOSL1/CIB2/ZEB1 pathway functioned in regulation of gefitinib resistance and CIB2 could be applied as a novel biomarker for diagnosis of drug resistance of lung cancer." (PMID 39264588, 2024). "The aim of this study is to investigate the role of CIB2 in lung cancer and chemoresistance." (PMID 39264588, 2024). "Similarly, CIB2 was highly expressed in lung cancer samples when compared to normal samples." (PMID 39264588, 2024). "Thus, whether CIB2 acts as an oncogene in lung cancer remains to be determined." (PMID 33227088, 2020). "In addition, the positive correlation of CIB2 and ZEB1 in lung cancer samples was analyzed with the GEPIA database." (PMID 39264588, 2024). "Like CIB2, IRF4 function in lung cancer remains to be clearly determined." (PMID 33227088, 2020). "In addition, the mRNA expression levels of CIB2 and ZEB1 were also upregulated in osimertinib-resistant lung cancer cell lines, which indicates that CIB2 and ZEB1 may contribute to osimertinib resistance." (PMID 39264588, 2024). "CIB2 induced tumor growth and gefitinib resistance by inhibiting cell apoptosis and enhancing EMT in NSCLC, and CIB2 could be applied as a novel biomarker for diagnosis of drug resistance of lung cancer." (PMID 39264588, 2024). "However, despite the high expression of CIB2 in gefitinib-resistant cells, the mechanism of CIB2 has not been revealed in lung cancer." (PMID 39264588, 2024).
viral infection (2 papers, 2016 to 2022). "In conclusion, our work demonstrates that knockdown of both CIB1 and CIB2 impaired an early step in receptor-mediated viral entry involved in both cell-free and cell-mediated viral infection, and was associated with reduced surface expression of CXCR4, CCR5 and α4β7." (PMID 27489023, 2016). "A lower expression of membrane proteins such as CXCR4, integrin α4β7, and CCR5 (in PM1 cell line) was indeed found in CIB2-knocked down T-cells, suggesting a potential role of at least one of these proteins in promoting viral infection." (PMID 35408910, 2022). "Knockdown of both CIB1 and CIB2 impaired an early step in receptor-mediated viral entry, and both cell-free and cell-mediated viral infections were affected." (PMID 27489023, 2016). "The finding that normal concentrations of CIB2 facilitate the virus entry could be used to develop treatments in the early stages of the viral infection." (PMID 35408910, 2022). "CIB1 and CIB2 knockdown were shown to reduce the expression of surface receptors implicated in HIV-1 infection, suggesting at least one mechanism through which these proteins promote viral infection." (PMID 27489023, 2016). "CIB1 and CIB2 knockdown was found to reduce the expression of surface molecules implicated in HIV-1 infection, including CXCR4, CCR5 and integrin α4β7, suggesting at least one mechanism through which these proteins promote viral infection." (PMID 27489023, 2016). "Taken together, our results indicate that the effects of CIB1 and CIB2 knockdown specifically affect early events in virus infection, encompassing receptor-mediated viral binding, membrane fusion, and possibly, early post-fusion modification of the cellular cytoskeleton." (PMID 27489023, 2016). "Taken together, these results indicate that both CIB1 and CIB2 play an important and non-redundant role in facilitating viral infection of Jurkat T-cells." (PMID 27489023, 2016).
diabetic foot ulcer (1 paper, 2025). "This study employed machine learning techniques to identify four key genes—DPYSL2, CIB2, IFI44, and SAMHD1—that potentially play a significant role in the pathogenesis and progression of diabetic foot ulcer (DFU) disease." (PMID 40487403, 2025).
HIV-1 infection (1 paper, 2016). The type species of lentivirus and the etiologic agent of acquired immunodeficiency syndrome (AIDS). "To palliate this uncertainty, we have undertaken a series of studies to better define the role of CIB1 and CIB2 in HIV-1 infection." (PMID 27489023, 2016). "The efficiency of HIV-1 infection can be improved by cell-to-cell transmission, raising the possibility that cell-to-cell transmission would abrogate the defect in infectivity seen following downmodulation of CIB1 and CIB2 expression." (PMID 27489023, 2016). "We found, however, that the viability of Jurkat cells and activated CD4+ T-lymphocytes either before or after HIV-1 infection was not influenced by CIB1 and CIB2 knockdown." (PMID 27489023, 2016).
lung adenocarcinoma (1 paper, 2024). A carcinoma that arises from the lung and is characterized by the presence of malignant glandular epithelial cells. "In addition, UALCAN database also conveyed that the CIB2 levels were greatly increased both in lung adenocarcinoma (LUAD) and lung squamous carcinoma tissues (LUSC)." (PMID 39264588, 2024).
non-small cell lung carcinoma (1 paper, 2025). A group of at least three distinct histological types of lung cancer, including non-small cell squamous cell carcinoma, adenocarcinoma, and large cell carcinoma. "In addition, CIB2 holds potential as a therapeutic target for overcoming epidermal growth factor receptor-tyrosine kinase inhibitor (EGFR-TKI) resistance in non-small-cell lung cancer (NSCLC)." (PMID 40076845, 2025).
retinal ciliopathy (1 paper, 2023). "Moreover, due to the presence of defects in photoreceptor cilia in cell and animal models for USH, evidence has been accumulating in recent years that USH is considered a retinal ciliopathy which is consistent with the ciliary association of CIB2 and ADGRV1 described here." (PMID 37427378, 2023).
tumor (5 papers, 2012 to 2025). "Our results further showed that the tumor volumes were larger in CIB2-overexpressed group compared to control, while treatment with gefitinib conveyed a slight growth inhibition in CIB2-overexpressed tumors compared to control." (PMID 39264588, 2024). "The tumor-suppressor role of CIB2 was investigated using specific OC cell lines, in which the re-expression of CIB2 led to hindered neoplastic growth, a 50% reduction in cell migration, and a higher response to carboplatin treatment." (PMID 35408910, 2022). "The tumor volumes were measured, and tumor weights were calculated at the end of the experiment; tumor weights were increased in CIB2-overexpressed group compared to control, and CIB2-overexpressed group treated with gefitinib showed a decline in tumor weights." (PMID 39264588, 2024). "Interestingly, the downregulation of CIB2 was found to be unrelated to tumor stage or grade, making this small protein a good candidate for early-stage diagnosis and a potential target to improve the efficacy of chemotherapy." (PMID 35408910, 2022).
cancer (2 papers, 2020 to 2024). A tumor composed of atypical neoplastic, often pleomorphic cells that invade other tissues. "Therefore, knockout of CIB1 or over-expression of CIB2 will result in sphingosine accumulation and contribute significantly to cancer treatment by several approaches." (PMID 33123153, 2020).
infection (1 paper, 2016). The state of being infected such as from the introduction of a foreign agent such as serum, vaccine, antigenic substance or organism. "Elucidation of the mechanisms through which CIB1 and CIB2 promote infection is likely to provide new insights into the strategies used by HIV-1 to co-opt normal cell functions to efficiently transfer capsids into the cytosol." (PMID 27489023, 2016). "As in Jurkat cells, CIB1- and CIB2-depleted CD4+ T-lymphocytes displayed a significant decrease in susceptibility to infection when challenged with HIV-1-enveloped particles but not with VSV-G-enveloped particles." (PMID 27489023, 2016). "The percentage of cells expressing intracellular Gag at day 3 post-infection with HIV-1NL4-3 was decreased by 70% and 60%, respectively, following down modulation of CIB1 and CIB2." (PMID 27489023, 2016). "Reducing the expression of both CIB1 and CIB2 also significantly decreased productive infection efficiency measured at 24 h, showing that CIB1 and CIB2 are required for both cell-free and cell-to-cell virus transmission." (PMID 27489023, 2016).
CIB2 also shares sentences with these, for which no sentence is quoted: Usher Syndrome type 1J (9 papers); Hearing impairment (3); retinitis pigmentosa (3); genetic disorder (2); retinal dystrophies (2); Blindness (1); breast carcinoma (1); cardiac hypertrophy (1); Congenital muscular dystrophy type 1A (1); prostate carcinoma (1); sarcopenia (1); valvular heart disease (1).